USP21 (ubiquitin specific peptidase 21)
Diseases named in the same sentence as USP21 in open-access papers (continued):
Sharing a sentence is not in itself a finding about the gene and the disease.
tumor (39 papers, 2017 to 2026). "Ubiquitin-specific protease 21 (USP21) has been implicated in tumor progression across multiple malignancies; however, its prognostic value in CRC has not been fully elucidated." (PMID 41918783, 2026). "As a result, depletion of USP21 decreases homologous recombination efficiency, causes an increase in DNA damage load and impairs tumor cell survival." (PMID 28743957, 2017). "Importantly, CRC with low USP21 exhibited higher tumor mutational burden, high PD-L1 expression, and better responsiveness to immunotherapy and chemotherapeutic drugs." (PMID 38834869, 2024). "In addition, multivariate analysis indicated that USP21 expression, tumor size, and N stage were independent risk factors for postoperative OS." (PMID 38385089, 2024). "To determine if the reduction in the growth of USP21-depleted tumor cells is functionally linked to the decrease in BRCA2 protein, we generated stable, BRCA2-transgenic HCC cell lines and followed clonogenic survival in the presence or absence of USP21 knockdown." (PMID 28743957, 2017). "Here, we identify the DUB enzyme USP21 as an HR-associated modulator of tumor cell survival." (PMID 28743957, 2017). "Finally, the regulatory axis of USP21/G3BP1 was demonstrated to be aberrantly activated in ESCC tumor tissues and closely associated with advanced clinical stages and unfavorable prognoses, which provides a promising therapeutic strategy targeting USP21/G3BP1 axis for ESCC patients." (PMID 38906857, 2024). "Multivariate Cox regression analysis further identified USP21 expression, tumor size, and N stage as independent prognostic factors for postoperative OS." (PMID 41301681, 2025). "Univariate analysis demonstrated that USP21 expression, patient sex, tumor size, tumor differentiation, N stage, and surgical margin were significantly correlated with overall survival (OS) in CCA patients." (PMID 41301681, 2025). "Subsequent correlation analysis between USP21 protein expression and clinicopathological characteristics of CCA patients revealed significant associations with tumor location and neural invasion." (PMID 41301681, 2025). "Molecular investigations uncovered that NMB protein stability is regulated through USP21-dependent deubiquitination, leading to subsequent activation of the NF-κB signaling cascade and tumor progression." (PMID 40486508, 2025). "To assess the tumorigenic potential of USP21, we conducted in vitro 3D tumor spheroid assays and in vivo xenograft assays using NSG mice." (PMID 39695128, 2024). "Subsequently, we further confirmed the role of USP21 in GEM resistance in CCA xenograft tumor models." (PMID 38385089, 2024). "Experimental evidence showed that upregulation of USP21 promotes cancer progression by stabilization of transcription factors crucial for tumor growth and metastasis." (PMID 39305962, 2024). "USP21 protein expression was significantly correlated with tumor location (p=0.034) and perineural invasion (p=0.002)." (PMID 38385089, 2024). "The study also examined the impact of USP21 on cytokine levels and immune cell infiltration in the tumor microenvironment (TME)." (PMID 38834869, 2024). "We analyzed a cohort of mCRC patients (n = 27), comparing USP21 expression in tumor tissues versus matched normal tissues." (PMID 39695128, 2024). "Presented results on HAP-1 cells indicate that USP21 regulates fundamental processes integral to tumor development and progression." (PMID 39305962, 2024). "The KEGG enrichment analysis showed that USP21 knockdown affected a variety of signaling pathways related to tumor and metabolism in CCA cells, among which Glycolysis/Gluconeogenesis and HIF-1 signaling pathway scored significantly higher than other pathways." (PMID 38385089, 2024). "Univariate analysis showed that USP21 expression, patient's gender, tumor size, tumor differentiation, N stage, and surgical margin were significantly correlated with OS in CCA patients." (PMID 38385089, 2024).
tumor (continued). "Subsequent examination by western blotting in randomly selected 14 pairs of samples showed that the USP21 protein level was upregulated in tumor tissues more than that of paired non-tumor tissues." (PMID 38385089, 2024). "Collectively, our study manifested the tumor-promoting regulation of the USP21/G3BP1 axis in ESCC progression." (PMID 38906857, 2024). "Collectively, all these reports suggested that the abnormal deubiquitinase of USP21 was crucial for its tumor-promoting function in most human cancers." (PMID 38906857, 2024). "We analyzed the differential expression levels of EGFR and USP21 in CRC tumor tissues compared to matched normal tissues from these patients." (PMID 39695128, 2024). "Further molecular studies demonstrated that the USP21/G3BP1 axis played a tumor-promoting role in ESCC progression by activating the Wnt/β-Catenin signaling pathway." (PMID 38906857, 2024). "Subsequently, we calculated the tumor mutational burden (TMB) scores in the TCGA-COAD cohort and observed a significantly higher TMB in low USP21 group compared to the high USP21 group." (PMID 38834869, 2024). "Compared with that in paired non-tumor tissues, the USP21 mRNA expression level was significantly upregulated in tumor tissues." (PMID 38385089, 2024). "Similar results were observed in 3D tumor spheroid formation assays conducted with USP21-KO HT-29 cells compared to Ctrl HT-29 cells." (PMID 39695128, 2024). "In xenograft and lung metastasis mice models, we found that USP21 downregulation obviously inhibited tumor growth rate, weight and Ki-67 protein expression and decreased metastatic nodules in mice lung." (PMID 38906857, 2024). "Tumor spheroids derived from USP21-KO HCT-15 cells were significantly smaller than those from Ctrl HCT-15 cells." (PMID 39695128, 2024). "The analysis based on the weight and volume of xenograft tumors showed that HSP90 knockdown partly diminished USP21-induced tumor growth." (PMID 38385089, 2024). "Having established that USP21 contributes to tumor formation triggered by EGF stimulation, we explored the impact of inhibiting USP21 activity using the pharmacological inhibitor BAY-805 on EGF-induced tumor formation." (PMID 39695128, 2024). "Concurrently, it is notable that conflicting functions have been reported where USP21 can act as an oncoprotein or a tumor repressor of cancer." (PMID 35846989, 2022). "The results showed that the xenografts carrying control shRNA GSCs exhibited more rapid tumor formation, while, in stark contrast, tumor growth was significantly repressed in the xenografts carrying GSCs with USP21 depletion." (PMID 35974001, 2022). "Considering the capacity of STING to sense cytosolic tumor-derived DNA in tumor-associated immune cells, as well as the ability of Treg cells to limit anticancer immunity and promote angiogenesis, these results together reinforce that targeting USP21 may offer promise for antitumor immunotherapies." (PMID 35846989, 2022). "Accordingly, the results of H&E staining indicated that the xenografts carrying USP21 shRNA GSCs displayed restricted tumor growth, whereas this effect is reversed by overexpression of FOXD1." (PMID 35974001, 2022). "In tumor research, USP21 is noted to participate in the malignant processes of a variety of cancers." (PMID 33791299, 2021). "In non-small cell lung cancer, USP21 promotes tumor cell proliferation, migration, and invasion through the YY1/SNHG16 axis." (PMID 33791299, 2021). "Mouse xenograft models were established to further analyze the effect of USP21 on tumor growth in vivo." (PMID 33791299, 2021). "It was also found that in the tumor tissue of the oe-USP21 group, USP21, GATA3, and MAPK1 were all pronouncedly highly expressed." (PMID 33791299, 2021). "We reported that USP21 promoted GC cell proliferation, migration, invasion, and stemness in vitro, and regulated GC tumor growth and cell stemness in mice in vivo." (PMID 33791299, 2021).
tumor (continued). "Due to the abnormal expression of USP21 in GC, AGS and MKN-45 cell lines which, respectively, had relatively low and high USP21 expression in all tumor cells were selected to study the relationship between USP21 and GC progression." (PMID 33791299, 2021). "USP21 promotes cell proliferation, tumor progression, and colony formation, and enhances cancer stem cell self-renewal." (PMID 32784507, 2020). "Expression of USP21 in patient tumor samples was represented by immunohistochemistry (IHC) score, which was obtained by multiplying the percentage of USP21-positive cells by staining intensity." (PMID 31947604, 2020). "In vivo tumor xenograft model assays indicated that YY1 knockdown abolished USP21 overexpression-induced tumor growth." (PMID 31956270, 2020). "Tumor volume and tumor weight were significantly increased in mice inoculated with USP21-overexpressing cells." (PMID 31956270, 2020). "Of note is that BRCA2 overexpression was unable to fully restore HCC tumor cell growth following USP21 knockdown." (PMID 29706623, 2018). "Altogether, these findings strengthen the idea that USP21 promotes cell cycle progression and tumor growth by stabilizing MEK2 and thereby activating ERK1/2 signaling." (PMID 29706623, 2018). "Biochemical dissection suggests that USP21 can associate with the C-terminal OB domains of BRCA2, and consistent with this, a tumor cell line with a C-terminal BRCA2 truncation is unresponsive to USP21 depletion with regard to BRCA2 stability and tumor growth." (PMID 28743957, 2017). "Mechanistically, we show that loss of USP21 in HCC cell lines results in a reduction of BRCA2, increased DNA damage accumulation and a concomitant tumor growth defect that partially depends on BRCA2." (PMID 28743957, 2017). "Here the authors show that USP21 regulates the ability of tumor cells to repair damaged DNA by regulating BRCA2 stability." (PMID 28743957, 2017). "A TCGA survey of USP21 mRNA expression revealed that 7 of the 26 interrogated cancer types showed significantly elevated USP21 levels when compared to non-tumor tissues (p < 0.001, Student’s two-tailed t-test)." (PMID 28743957, 2017). "USP21 stabilizes BRCA2 in patient-derived HCC tumor cell lines, protects from DNA damage and promotes tumor cell growth in a BRCA2-dependent manner." (PMID 28743957, 2017). "We now show that USP21 interacts with and deubiquitinates BRCA2 and that USP21 loss results in decreased BRCA2 expression in tumor cell lines." (PMID 28743957, 2017). "Of note, the tumor-promoting effects of USP21 are likely to go beyond the modulation of HR and/or BRCA2 stability, as BRCA2 overexpression was unable to fully restore HCC tumor cell growth." (PMID 28743957, 2017). "Only three DUBs, including USP21, showed a greater than twofold increase in expression compared to non-tumor tissue." (PMID 28743957, 2017). "USP21 protein expression in tumor and adjacent normal tissues was assessed by immunohistochemistry." (PMID 41918783, 2026). "Additionally, pharmacological inhibition of USP21 with BAY-805 effectively reduced EGF-induced tumor spheroid formation, highlighting its therapeutic potential." (PMID 40629473, 2025). "In vivo, USP21 depletion significantly suppressed tumor growth in xenograft models." (PMID 40629473, 2025). "Conversely, upregulating USP21 induced GEM resistance in tumor cells." (PMID 38385089, 2024). "Moreover, it was noted that immune scores, stromal scores, and ESTIMATE scores were markedly reduced in the high USP21 group, with a positive correlation observed between tumor purity and USP21." (PMID 38834869, 2024). "We found that USP21 plays a key role in the regulation of tumor aerobic glycolysis." (PMID 38385089, 2024). "Additionally, USP21 mRNA levels in 10 cases of fresh ESCC tumor samples were obviously upregulated compared with adjacent normal tissues." (PMID 38906857, 2024).
tumor (continued). "Additionally, our results show that the pharmacological inhibition of USP21 with BAY-805 significantly reduces EGF-induced tumor formation in vitro, suggesting the therapeutic potential of targeting USP21 in mCRC treatment." (PMID 39695128, 2024). "In pancreatic cancer, USP21 activation promotes tumor growth via Wnt pathway activation." (PMID 38385089, 2024). "Likewise, functional experiments confirmed that USP21 promoted tumor growth in a HIF1A-dependent manner." (PMID 38385089, 2024). "Further analysis based on IHC evaluation exhibited that ESCC tumor tissues at advanced statuses of primary tumor (T3-4) or with regional lymph node metastasis (N1-3) had higher levels of USP21 protein compared with those at early primary tumor statuses (T1-2) or without positive lymph nodes (N0)." (PMID 38906857, 2024). "Additionally, poorly differentiated (G3) ESCC tumor samples displayed increased USP21 protein levels compared to well/moderately differentiated (G1-2) tumors." (PMID 38906857, 2024). "We further investigated the role of USP21 in EGF-induced 3D tumor spheroid formation." (PMID 39695128, 2024). "There is a positive correlation between the elevated expression of USP21 and high mortality in patients; therefore, small interfering RNA (siRNA) knockdown of USP21 and consequent reduction of tumor cell proliferation may be a promising treatment for DLBCL." (PMID 39664521, 2024). "Similarly, tumor spheroids grew progressively in Ctrl HT-29 cells but were notably smaller in USP21-KO HT-29 cells (J: USP21-KO HT-29 vs. Ctrl HT-29)." (PMID 39695128, 2024). "Notably, pharmacological inhibition of USP21 with BAY-805 markedly suppresses CRC tumor spheroid formation, highlighting the therapeutic potential of targeting USP21 in mCRC." (PMID 39695128, 2024). "mCRC patients with upregulated USP21 may experience more aggressive cancer progression, especially in an EGF-rich tumor microenvironment, compared to those with downregulated USP21." (PMID 39695128, 2024). "High expression of USP21 was closely correlated with tumor metastasis and tumor size." (PMID 37215134, 2023). "Examination of whether NEDA can induce HCC in Usp21-deficient mice may further deepen our understanding of the oncogenic role of Usp21 at the tumor initiation stage." (PMID 35846989, 2022). "Furthermore, it was also proved in nude mice that overexpression of USP21 stimulated the tumor growth and cell stemness of GC in vivo." (PMID 33791299, 2021). "Taken these findings together, it could be seen that USP21 regulated tumor growth and cell stemness of GC in vivo." (PMID 33791299, 2021). "IHC analysis also showed stronger staining of USP21 in NSCLC tumor tissues than adjacent tissues." (PMID 31956270, 2020). "However, tumors in the experimental group of USP21 knockdown were smaller and less numerous as presented by the percentage of the tumor forming area: 4.2% in the USP21 knockdown group and 24% in the control group (bottom)." (PMID 31947604, 2020). "To gain mechanistic insights into USP21 function in HCC, we asked whether USP21 can modulate MEK2 stability in HCC-derived tumor cells." (PMID 29706623, 2018). "Since MEK2 can rescue the down-regulation of ERK1/2 phosphorylation induced by USP21 inhibition, we investigated whether USP21 functions as a tumor-promoting protein by regulating MEK2." (PMID 29706623, 2018). "Ectopic USP21 expression significantly accelerated the rate of tumor growth." (PMID 29706623, 2018). "Together, these findings point to a unique, tumor-promoting role for USP21 in HCC." (PMID 28743957, 2017). "We thus reasoned that USP21 depletion and the associated reduction in BRCA2 may result in a similar tumor growth defect." (PMID 28743957, 2017). "It is tempting to speculate that low USP21 may contribute to tumor formation early in cancer development, but that this effect might be obscured by secondary genetic changes including amplification of region 1q21." (PMID 28969054, 2017).
tumor (continued). "In addition, we investigated the role of ENO1 in USP21-mediated CCA tumor progression." (PMID 38385089, 2024). "Simultaneously, gallic acid can enhance the anti-tumor effect of anti–PD-1 immune checkpoint blocking and downregulate the expression of PD-L1 protein in Tregs, indicating that the deubiquitinating enzyme Usp21 can deubiquitinate and stabilize the PD-L1 protein." (PMID 38807592, 2024). "Therefore, the tumor-suppressive effects of USP21 need to be confirmed in further studies." (PMID 35846989, 2022). "Importantly, we provide evidence that a defect in USP21-mediated BRCA2 stabilization impairs the growth of BRCA2-proficient HCC tumor cells, and consistent with this, USP21 levels inversely correlate with HCC patient survival, pointing to USP21 as a potential target for HCC tumor therapy." (PMID 28743957, 2017). "The normal activity of USP21 may contribute to tumor suppression." (PMID 28969054, 2017). "The effects of USP21 knockdown, TACE and their combination on tumour growth, proliferation, invasion and apoptosis were evaluated." (PMID 42298713, 2026). "Our investigation into the interaction between USP21 and TME demonstrated the heightened malignancy and poorer prognostic outcomes observed in CRC with high USP21, from the perspective of tumor immunity." (PMID 38834869, 2024). "Conversely, in USP21-KO HCT-15 cells, the size of tumor spheroids was noticeably smaller when treated with vehicle compared to vehicle-treated Ctrl HCT-15 cells (E: USP21-KO HCT-15 treated with vehicle vs. Ctrl HCT-15 treated with vehicle)." (PMID 39695128, 2024). "Presented results provide new insights into the biology of USP21, suggesting novel mechanisms for controlling STAT3 activity and mitochondrial function in tumor cells." (PMID 39305962, 2024). "In summary, our findings highlight that USP21-mediated post-translational regulation of HSP90 and ENO1 is important in aerobic glycolysis and CCA tumor progression and provide an option for cancer therapy targeting glucose metabolism." (PMID 38385089, 2024). "High USP21 in CRC engenders an immunosuppressive TME, thwarting the immune system's anti-tumor efficacy." (PMID 38834869, 2024). "To ascertain the influence of USP21 in CRC on immunotherapy, we conducted validation within cohorts of tumor patients undergoing diverse treatment regimens." (PMID 38834869, 2024). "Conversely, knockout of USP21 (USP21-KO) in CRC cells impairs cancer progression and reduces tumor formation following EGF stimulation." (PMID 39695128, 2024). "Similar to USP21, higher protein levels of G3BP1 were found in ESCC tissues with T3-4 or N1-3 when compared to tumor samples with T1-2 or N0." (PMID 38906857, 2024). "Functional studies were performed, including the use of CRISPR/Cas9 to generate USP21-knockout (USP21-KO) CRC cells, in vitro assays for cancer progression and tumor formation, in vivo xenograft assays in NSG mice." (PMID 39695128, 2024). "Hence, targeting USP21 could be helpful to improve tumor immunotherapy." (PMID 37215134, 2023). "The expression of USP14, USP21 and PSMD14 significantly increases within tumor tissue from liver cancer patients, which is negatively correlated with survival rate." (PMID 37251574, 2023). "USP21 can catalyze the deubiquitination of MEK2, thereby activating the ERK pathway, inducing cell proliferation and promoting tumor growth." (PMID 37251574, 2023). "It has been reported that USP2a, USP7, USP21, and USP22 are highly expressed in the HCC tissue or cells and promote tumor development." (PMID 35669517, 2022). "Accordingly, depletion of USP21 markedly reduced GSC tumorigenicity and prolonged the survival of tumor-bearing mice." (PMID 35974001, 2022). "All these effects can be reversed by ectopic expression of FOXD1, thus strongly supporting our notion that USP21-mediated FOXD1deubiquitination sustains MES properties of GSCs, and eventually contributes to tumor progression in GBM." (PMID 35974001, 2022).